TF (transferrin)
Diseases named in the same sentence as TF in open-access papers (continued):
Sharing a sentence is not in itself a finding about the gene and the disease.
tumor (continued). "Dual doxorubicin-and verapamil-loaded liposomes with surface-conjugated transferrin successfully inhibited the doxorubicin-resistant K562 leukemia tumor cell line with about 5-fold greater potency compared to non-targeted, doxorubicin/verapamil loaded liposomes." (PMID 25013742, 2013). "In addition, the liposomes can be functionalized with ligands for tumor-specific receptors, such as transferrin, folate, and integrin." (PMID 25013742, 2013). "A significant correlation of 99mTc-TF uptake with proliferation index and tumor grade was found." (PMID 22623896, 2012). "Finally, overexpression of the TfR by many cancer cells has promoted interest in the use of transferrin for tumor imaging and targeted drug delivery." (PMID 21083917, 2010). "Therefore tagging a drug or image contrast agent to transferrin for specific delivery to tumor cells emerged as a promising strategy and is being widely explored for tumor-targeted delivery." (PMID 16476163, 2006). "Our results show that especially the transferrin-bound forms exhibit high antiproliferativeactivity, which exceeds that of the free complex, indicating that this protein can act as acarrier of the ruthenium complexes into the tumor cell." (PMID 18472789, 1996). "These tumor-associated carbohydrate antigens (TACAs) include GalNAcα-O-Ser/Thr (Tn, Thomsen Nouveau, CD175), Neu5Acα2,6-GalNAcα-O-Ser/Thr (sTn, sialyl Tn, CD175s), Galβ1,3-GalNAcα-O-Ser/Thr (TF, Thomsen–Friedenreich, CD176, T), Neu5Acα2,3-Galβ1,3-GalNAcα-O-Ser/Thr (sTF, sialyl TF)." (PMID 41154387, 2025). "In addition, since EMT represents a hallmark of SCLC, the increased EMT TF expression in PBMC-EXs from NR patients may be involved in the crosstalk between PBMC-EXs and cancer cells and modulate tumor response." (PMID 39335123, 2024). "In addition, we identified other ligand-TF pairs potentially modulating CMS2 tumor progression." (PMID 38200223, 2024). "Finally, we discovered that the 12 IMRGs expression had significant differences, among which SFXN3, TFR2, TMPRSS6, HMOX1, and LCN2 expressions were elevated in the cancer group, and SCARA5, LTF, STEAP2, SLC39A14, CP, ALAS2, and TF were low expressed in the tumor group." (PMID 37361050, 2023). "Overall, we found that at metastatic sites the uptake of labeled transferrin may be variable, and that high physiological expression of TfR and TfR2 by target organs can affect the ability of Tf-conjugates to identify tumor sites, particularly for smaller lesions." (PMID 38117806, 2023). "Moreover, transferrin-modified nanoparticles can enhance drug delivery efficiency in tumor cells." (PMID 37122851, 2023). "TF is also known as Transferrin which is essential for ferric iron transporting into cells and could influence iron metabolism in human, and might be involved in ferroptosis regulation in tumor cells indirectly." (PMID 36998462, 2023). "Indeed, procoagulant, PS-expressing tumor-derived EVs provide initiation sites for blood coagulation and tumor-derived EVs may activate platelets and promote their aggregation through both TF-dependent and TF-independent mechanisms." (PMID 36013171, 2022). "Finally, one TF, BACH1, was found to be significantly upregulated in C1 subtypes; the pathways activated by this TF may be associated with tumor progression and poor prognoses." (PMID 35801241, 2022). "As such, tumor heterogeneity, especially with regards to the diversity, density and steric complementarity of cell surface adhesion molecules (e.g., TF antigen, Cadherins, galectin-3, EpCAM, Na+/K+-ATPase, and glycoprotein 100, etc.)may prove to be extremely difficult to address in the clinic." (PMID 34070233, 2021). "Moreover, the coating allows loading of specific ligands, antibodies, peptides, drugs, folic acid, aptamers, tumor markers, transferrin, vitamins, etc., on the surface of particles offering an exciting tool to make NPs target-specific and increase their therapeutic benefit." (PMID 33287297, 2020).
tumor (continued). "In addition, transferrin can act as a moderate selective carrier towards tumor cells." (PMID 31394747, 2019). "Furthermore, we have uncovered other receptors, intermediary signal transduction proteins and TF targets that may drive oncogenesis: all of which could be targeted by drugs designed to specifically treat QM- C- or EL-PDAC tumours." (PMID 30018740, 2018). "In vivo anti-tumor efficacy studies demonstrate a higher tumor inhibition rate of 45.1% for paclitaxel–transferrin formulation compared to 28.8% for paclitaxel nanosuspension treatment alone, and paclitaxel–transferrin formulation showed a lower level of toxicity." (PMID 30134537, 2018). "The overexpression of TF and its non-procoagulant isoform, alternatively spliced TF (asTF), were found both to facilitate tumor progression experimentally and to be associated with poor prognosis clinically, thus leading to worldwide studies of TF and its isoform in cancer therapy." (PMID 28106852, 2017). "In addition, TF and asTF were indicated to play a role in tumor progression in several studies, indicating their role in promoting cell proliferation, tumor angiogenesis, and clot formation in the circulation, which was directly linked to cancer-associated VTE." (PMID 28106852, 2017). "Interestingly, MCF-7 cells have been reported to synthesize their own transferrin in an estrogen-dependent manner that may act in an autocrine fashion to stimulate Fe uptake by tumor cells, and thus, proliferation." (PMID 24586383, 2014). "However, it is currently unknown which molecules stabilize tumor/endothelial cell adhesion downstream of TF-Ag/Gal-3 interactions." (PMID 24675526, 2014). "Importantly, our data suggests that the effect of TF-SB on tumor growth and invasion might occur through decreasing expression of MMPs, and increasing expression of TIMP." (PMID 23344202, 2013). "By analyzing TF expression and regulatory activity in different tumor cell subtypes, we determined that the M1 module mainly regulated the C0 TSPAN1+ tumor EPCs." (PMID 40777026, 2025). "Furthermore, in the metastatic microenvironment, tumor cells produce large amounts of granulocyte‒macrophage colony‒stimulating factor (GM-CSF), which specifically targets neutrophils via activation of the Jak/Stat5β pathway, thereby upregulating transferrin gene expression." (PMID 40528159, 2025). "After being modified with transferrin (Tf), the nanogels (PMEDAPA-Tf) achieve tumor targeting at hyperthermia, leading to enhanced tumor accumulation." (PMID 40871082, 2025). "Transferrin and RGD motif are examples of cell-specific ligands which are utilized to target specific receptors on tumor cells." (PMID 39861768, 2025). "Further analysis of ferroptosis pathway proteins, including TF, GCLC, and GCLM, demonstrated differential involvement in TIMP1-overexpressing and TIMP1-knockout cells and tumor tissues." (PMID 40185230, 2025). "Active targeting ligands, such as transferrin or integrin-binding peptides, can further enhance BBB penetration and tumor targeting." (PMID 40365286, 2025). "Based on the results of IHC staining, the levels of the cell proliferation markers Ki67 and GPX4 were reduced in BALB/c mouse-derived tumor tissues following BCHE treatment, while transferrin expression was upregulated." (PMID 38906931, 2024). "Ligand-receptor analysis between macrophages and tumor cells identify C5/C5AR1,SPP1/ITGA4, and TF/TFRC as the ligand-receptor signaling mechanism driving these niche-DE genes." (PMID 38217002, 2024). "Several studies have demonstrated that reducing iron intake, lowering the concentration of transferrin and its receptor (TfR) in the body, or increasing the expression of FPN on the cell membrane can inhibit tumor proliferation." (PMID 39061859, 2024). "We therefore generated an anti-TF/-CD3 BiTE from the TF8-5G9 and OKT3 scFv which successfully targeted both the TF tumour cell and CD3 of T cells." (PMID 39105809, 2024).
tumor (continued). "Another explanation is that when tumor cells undergo EMT, the demand for iron increases, which is accompanied by a shift in the way cells absorbing iron, from TfR1-mediated transferrin to CD44-mediated hyaluronic acid-iron complex as the main approach." (PMID 36910614, 2023). "The three Hub TF genes are highly upregulated in TNBC and affect the proliferation of tumor cells through the PI3K-Akt signaling pathway, Wnt signaling pathway, FOXO signaling pathway, and mTOR signaling pathway, resulting in a poor prognosis." (PMID 37686305, 2023). "It was found that high TF was closely connected to AFP (p = 0.033) and the tumor size (p = 0.034) and number (p = 0.020)." (PMID 36614249, 2023). "TF expression is upregulated in more aggressive EMT+ cells and CTCs, providing tumor cells with enhanced coagulant properties that facilitate early steps of metastatic colonization." (PMID 38028589, 2023). "The TF-protein, SOX2, has been found to be a tumor promoter and has a dynamic therapeutic strategy for TNBC." (PMID 36567949, 2022). "For example, the pH-responsive DHA-GO-TF and TF-8arm-PEG-DHA delivery systems both showed higher solubility, enhanced tumor delivery specificity, minimal side-effects, and superior tumor growth restrained ability in vivo." (PMID 35214127, 2022). "The internalization of FITC-labeled, transferrin-functionalized B4C NPs was shown by confocal images in HeLa cells overexpressing the transferrin receptor and confirmed by TEM in mouse ex vivo tumor tissues." (PMID 36552793, 2022). "In response to tumor-derived granulocyte–macrophage colony-stimulating factor (GM-CSF), neutrophils secrete high levels of transferrin (TRF), an iron transporter and potent mitogen, thus enhancing tumor growth and metastasis." (PMID 36555469, 2022). "Then, as a crucial tumor suppression factor of PCa epithelium, protein SMAD2 is inhibited, resulting in TF ESF1 upregulation and oxidatively induced DNA damage." (PMID 35164166, 2022). "Tumor markers are clinically detected by serum biochemistry due to abundant serum proteins, including human serum albumin (HSA), immunoglobulin (IG), transferrin, and α-antitrypsin." (PMID 36551243, 2022). "On the other hand, owing to the fact that TF RBMX, a kind of tumor suppressor, loses its function, its low expression is related to a high fructose diet and the synthesis of cholesterol." (PMID 35164166, 2022). "We showed that the SOX2 reprogramming TF that drives GBM cell stemness and tumor-propagating potential induces miR-10b-5p that targets TET2 that we show inhibits GBM cell stemness and GBM xenograft growth." (PMID 35136034, 2022). "For example, hepcidin, ferritin, transferrin, and transferrin receptor 1 (TFR1) levels are higher in tumor cells than in normal cells." (PMID 34962017, 2022). "In preliminary tests, we attached transferrin, chosen because it enables nanoparticle penetration across the BBB/BTB and enhances uptake into tumor cells due to their upregulated TfR (transferrin receptors)." (PMID 35335886, 2022). "Several researchers have reported the synthesis of transferrin-modified MgO2 nanosheets (TMNSs), which have a similar reaction to the neutral pH and low CAT activity of the tumor microenvironment." (PMID 36568636, 2022). "Tissue factor (TF, also known as coagulation factor III or CD142), expressed by tumor cells, triggers the formation of a platelet clot around the tumor cells." (PMID 34208889, 2021). "For example, several complement proteins interact with tissue factor (TF; Factor III) and TF-bearing microparticles produced by tumor cells." (PMID 34671342, 2021). "Seventy-two paired tumor and adjacent normal tissues in the TCGA KIRC cohort were utilized to investigate the TF gene expression profile to explore the dysregulated TFs in ccRCC." (PMID 34124141, 2021).
tumor (continued). "In this study, ERN was loaded into liposomes by ethanol injection (LP-ERN), and the resulting LP-ERN nanoparticles were treated with transferrin to form Tf-LP-ERN to improve the solubility and enhance the tumor-targeting of ERN." (PMID 34513705, 2021). "This complex targets tumor sites through both the enhanced permeability and retention (EPR) effect and TF/TFR interaction." (PMID 33892746, 2021). "Surface-modified transferrin is specific to the upregulated transferrin receptors in HCC cells and facilitates targeted tumour delivery and high intracellular DOX accumulation." (PMID 34749740, 2021). "TF and TFRC are two key molecules in transportation of iron ion during ferroptosis, and both genes were low expressed in tumor tissues." (PMID 34906147, 2021). "Accumulation of gallium in some tumours is a known phenomenon, probably in part due to its similarity to Fe(III), which allows gallium to bind to transferrin and hence delivery to tissues overexpressing transferrin receptors." (PMID 32098299, 2020). "In order to improve the tumor specific delivery of MSN carrier, transferrin (Tf) which is a ligand of TFR1, has been widely exploited in surface modification of MSN." (PMID 32521802, 2020). "SPECT-CT with attenuation correction showed an overall increase in In-111-neutrophil clearance into tumour with a median of 0.0103 mL/min/mL (IQR; 0.0021–0.0387) compared with a median of 0.0037 mL/min/mL for In-111-transferrin clearance (IQR; 0.0008–0.0066)." (PMID 32887739, 2020). "TF harbors seven CpG sites (three DMSs) in its TSS1500 and TSS200 regions, and is known to play key roles in drug delivery in TNBC tumor cells." (PMID 31690011, 2019). "The transferrin (TfR) and epidermal growth factor receptors (EGFR) are known to be overexpressed on the surface of a wide variety of tumor cells." (PMID 29315261, 2018). "Moreover, transferrin may prove especially lucrative for bioimaging due to its natural capacity to carry iron; as a result, MRI imaging may allow for a clearer tumor outline and thereby be of aid during surgical resection, especially when conjugated alongside magnetic C-dots." (PMID 29439409, 2018). "For siRNA delivery, this approach led to increased tumor-specificity of RNA delivery in vivo, but only if tumor-specific ligands (EGFR binding peptide, transferrin protein, or folate, see next section) were applied." (PMID 28963371, 2017). "For example, we showed that the mRNA levels of transferrin (TF), Apolipoprotein A1 (APOA1) and hepatocyte nuclear factor 4-alpha (HNF4α) were significantly altered in AA liver (cirrhotic) and tumor samples compared to CA." (PMID 28938650, 2017). "As a result, TF-HA-CMC-PLGA NPs enhances the therapeutic effects of HA and achieves a significant tumor inhibition effect." (PMID 29209206, 2017). "The inhibitory effect of total flavonoids on tumor growth in mice was better than that of CTX, and the inhibitory effect of TF on tumor growth was less than CTX." (PMID 28903343, 2017). "UNG, FUCA2, DERA, GMFB, TF, and SNX24 as significantly downregulated upon mir-145 over-expression, are expected to have elevated expressions in tumor samples considering low levels of miR-145 in several cancer types." (PMID 27655328, 2016). "One way to enhance tumor selectivity is to attach tumor-specific ligands (e.g., HER2 antibody, aptamers, and transferrin) to target signal transduction pathways in cancer." (PMID 26751490, 2016). "The groups treated with free DHA and different nanoparticles showed varied levels of survival time and they were ranked as TF-8arm-PEG-DHA NPs > 8arm-PEG-DHA NPs > DHA, which was consistent with the results of tumor growth inhibition." (PMID 27377918, 2016). "The EVs isolated from tumor cells express, for example, FasL, MHC classes I and II, mRNA, miRNA, FADD, P-glycoprotein, MMPs, PS, and TF." (PMID 26380326, 2015).
tumor (continued). "In this liposomal formulation, the receptor-targeting properties of transferrin and RGD were combined with the enhanced cell uptake effect to improve the transport of desired cargo to the tumor." (PMID 25289086, 2014). "Transferrin (TF) is a specific ligand for the TF receptor (TFR), which is overexpressed in the BBB and tumor cells." (PMID 25289086, 2014). "It is reported that transferrin is induced by SREBP2, a master regulator of cholesterol homeostasis, which in turn inhibits reactive oxygen species and drug-induced ferroptosis, thereby promoting tumor metastasis." (PMID 39810853, 2025). "Transferrin-SPIONs (Tf-SPIONs) bind transferrin receptors (TfR), while lactoferrin-SPIONs (Lf-SPIONs) engage lactoferrin receptors (LRP1), facilitating receptor-mediated endocytosis into tumor cells." (PMID 41583439, 2025). "The current work designed a transferrin-conjugated BP-based nanoplatform co-loaded with doxorubicin and functionalized with PDA, offering active tumour targeting, pH/NIR-triggered release, and enhanced therapeutic synergy through chemo–photothermal–photodynamic modalities." (PMID 40822245, 2025). "Meanwhile, in both MC38 cells after coculture treatment and tumor tissue with HFD administration, the transferrin (TRF) expression was elevated, but this could be remarkedly reversed by SGF, indicating the involvement of iron metabolism in ferroptosis." (PMID 40141120, 2025). "The TF/FVIIa complex activates the extrinsic coagulation cascade, but the role of HSAT in regulating TF/FVIIa activity in the tumor microenvironment has not been evaluated." (PMID 40924474, 2025). "Transferrin conjugation on the liposomal surface is an effective strategy for targeting the delivery of drugs across the BBB and increasing its accumulation at the tumor site." (PMID 39457052, 2024). "Because the TF8-5G9 anti-TF CAR showed no reaction to murine TF, this would allow in vivo mouse experiments to performed without concern of any on-target off-tumour effects of using this particular scFv clone." (PMID 39105809, 2024). "Furthermore, CuO2@G5-BS/TF induced ferroptosis and cuproptosis in 4T1 cells by depleting GSH and overloading copper and iron, while also alleviating the acidity of the tumor microenvironment, thereby inhibiting tumor metastasis." (PMID 39309446, 2024). "In vivo, intravenous injection of PLB-encapsulated transferrin-loaded liposomes resulted in tumour suppression in 10% of B16-F10 tumours and tumour regression in a further 10%, without any evidence of toxicity." (PMID 39275349, 2024). "Interestingly, results indicate that SAS treatment increased transferrin and STEAP-3 expression, while decreased ferritin, SLC7A11, and GPx-4 expression, which are the major drivers that protect the tumor cells from ferroptosis." (PMID 39513121, 2024). "Furthermore, IHC staining and immunoblotting analysis of BALB/c mouse-derived tumor tissues suggested that BCHE reduced GPX4 expression and increased transferrin expression in vivo." (PMID 38906931, 2024). "Since serum ferritin is not well suited to assess iron status in tumor patients, it is better to determine transferrin saturation." (PMID 38240843, 2024). "Strikingly, tumor cells with higher levels of fixation of ACA and WGA (recognizing TF-antigen and GlcNAc residues respectively) were found in patients with worse OS, whereas tumor cells with higher levels of fixation of HPA (recognizing terminal αGalNAc) were found in patients with a better PFS." (PMID 36891308, 2023). "Tumor can product multiple inflammatory factors, such as IL1, TNFα and VEGF, which can induce endothelial cell activation, promote leukocyte recruitment and platelet adhesion, and generate FVIII and TF that accelerate thrombosis." (PMID 37386391, 2023). "Third, the nanoplatelets were removed exclusively by the liver and spleen, and the transferrin-coupled nanoplatelets had a stronger tumor-targeting effect than the control nanoplatelets without transferrin." (PMID 36836127, 2023).